FOXA1 (forkhead box A1)
Diseases named in the same sentence as FOXA1 in open-access papers (continued):
Sharing a sentence is not in itself a finding about the gene and the disease.
bladder cancer (continued). "Should future studies reveal a significant relationship between FOXA1 loss and gender, the fact that FOXA1 has been described as a “master” of steroid receptor function in malignancy indicates further studies of the relationship between FOXA1 expression and gender in bladder cancer are warranted." (PMID 22590586, 2012). "In the context of bladder cancer, FOXA1 expression exhibits a spectrum of alterations, ranging from absence to increased or modified expression, with these anomalies associated with different molecular subtypes." (PMID 38425344, 2024). "We therefore sought to determine if ZBED2 is involved in the downregulation of interferon signaling in bladder cancer, potentially through interfering with FOXA1-activated pathways." (PMID 36944729, 2023). "We further illustrate this relationship with two well-described example markers of bladder cancer subtypes: FOXA1 and KRT6A." (PMID 36944729, 2023). "This strategy identified a large module of Luminal TFs, including known Luminal-associated TFs (e.g., FOXA1/GATA3/PPARG), as well as TFs with yet unexplored roles in Luminal bladder cancer biology (e.g., HES1, FOXQ1, ZBTB7C, MECOM, GRHL2/3, and TBX3)." (PMID 36944729, 2023). "LINC00482 promotes MMP15 expression by recruiting FOXA1, leading to the inhibition of inflammation and angiogenesis in bladder cancer, consistent with our results." (PMID 36879212, 2023). "To explore this possibility, we generated a series of FOXA1 knockout (FOXA1-KO) sublines through CRISPR-Cas9 mediated gene editing of UM-UC-1 bladder cancer cells." (PMID 36323682, 2022). "We also confirmed that there was a reciprocal relationship between FOXA1 and PD-L1 expression in human bladder cancers using RNA sequencing data from the bladder cancer TCGA cohort (Spearman correlation; r = −0.45; p < 0.001)." (PMID 36323682, 2022). "Conversely, ectopic expression of FOXA1 in UM-UC-3 cells, a bladder cancer cell line with high basal PD-L1 expression, was sufficient to downregulate CD274/PD-L1 expression." (PMID 36323682, 2022). "Experimental evidence suggests that the altered expression of certain transcription factors, such as Foxa1, Gata3, and Pparg, can affect the molecular subtypes of bladder cancer." (PMID 36077697, 2022). "In a recent study on subtype-specific chromatin states in bladder cancer, the pioneer factors FOXA1 and GATA3 were each found to serve as “loop anchors”." (PMID 35902807, 2022). "Both FOXA1 and GATA3 also play a role in the differentiation of urothelial cells in human bladder cancers, and the expression of PPARγ, FOXA1 and GATA3 is negatively correlated to the grade of the tumor." (PMID 36293167, 2022). "Using isogenic bladder cancer cells in which FOXA1 was genetically ablated using CRISPR/Cas9, we were able to show that loss of FOXA1 expression was sufficient to induce PD-L1 expression in bladder cancer cells." (PMID 36323682, 2022). "FOXA1 is an emerging regulator of the luminal subtype of bladder cancer, and FOXA1 overexpression can drive basal bladder cancer cells to assume a more luminal phenotype." (PMID 34831307, 2021). "In BC cell lines, studies by others have shown that have shown that GATA3 and FOXA1 cooperate with PPARγ activation to drive the differentiation of a basal bladder cancer subtype to a more differentiated luminal subtype." (PMID 32822399, 2020). "The present study demonstrated that LINC00482 induced the expression of MMP15 by interacting with FOXA1, thereby contributing to the inflammation and angiogenesis in bladder cancer." (PMID 33323547, 2020). "Expression of two copies of mutant HRAS results in the development of noninvasive bladder cancer at 6 months, and we saw identical urothelial regression in these animals following Upk2-Cre mediated Foxa1 KO." (PMID 30670749, 2019).
bladder cancer (continued). "They used the non-tumorigenic RT4 cell line engineered to exhibit a low expression of FOXA1 and conducted tissue recombination experiments to determine the influence of decreased FOXA1 expression on bladder cancer cell proliferation." (PMID 28915710, 2017). "Using the molecular subtype assignments, and our own RNA-seq analysis, we found overexpression of GATA3 and FOXA1 cooperate with PPARɣ activation to drive transdifferentiation of a basal bladder cancer cells to a luminial phenotype." (PMID 27924948, 2016). "We next performed crystal violet growth assays to identify a potential role for FOXA1 expression in the regulation of bladder cancer cell proliferation." (PMID 22590586, 2012). "Our observation that expression of FOXA1 and the proliferation marker Ki67 in human bladder cancer specimens is largely mutually exclusive suggests alterations in FOXA1 expression influence bladder cancer cell proliferation." (PMID 22590586, 2012). "We examined FOXA expression in commonly used in vitro models of bladder cancer and in human bladder cancer specimens, and used a novel in vivo tissue recombination system to determine the functional significance of FOXA1 expression in bladder cancer." (PMID 22590586, 2012). "As FOXA1 expression was associated with UPK in RT4 and 5637 cells, we investigated the expression of these markers in human bladder cancer specimens." (PMID 22590586, 2012). "Loss of E-Cadherin expression has been repeatedly implicated in the aggressive behavior of bladder cancer, and future work is planned to investigate the link between FOXA1 and E-cadherin in bladder cancer." (PMID 22590586, 2012). "While this is the first study of FOXA1 expression in bladder cancer, there is extensive evidence supporting its role in urothelial differentiation." (PMID 22590586, 2012). "The gene for FOXA1 is located on chromosome 14 q, and we found that FOXA1 expression was uniformly present in Ta stage tumors, but was lost in Stage T2 or higher bladder cancers." (PMID 22590586, 2012). "In vivo recombination of bladder cancer cells engineered to exhibit reduced FOXA1 expression with embryonic rat bladder mesenchyme and subsequent renal capsule engraftment resulted in enhanced tumor proliferation." (PMID 22590586, 2012). "In further support of this conclusion, overexpression of FOXA1 in T24 bladder cancer cells significantly decreased in vitro proliferation." (PMID 22590586, 2012). "In this context, it is known that IFN could antagonize the oncogenic effect of the transcription factor FOXA1 in bladder cancer." (PMID 40353763, 2025). "Since tretinoin is established as a differentiation therapy in acute leukemia, we sought to determine whether tretinoin treatment could induce the expression of GATA3 and FOXA1, which are key markers driving the luminal phenotype of bladder cancer." (PMID 38539513, 2024). "One research on bladder cancer found that overexpression of GATA3 and FOXA1 could influence the expression of markers associated with the luminal molecular subtype, suggesting potential molecular connections in UTUC." (PMID 38425344, 2024). "To determine if FOXA1, through its binding to the SE repertoire, regulates the bladder cancer epigenetic landscape and subsequently cellular identity, we produced FOXA1 CRISPR mutant clones allowing long-term FOXA1 inactivation in two Luminal cell lines (SD48 and RT112)." (PMID 36944729, 2023). "We identified FOXA1 as one of our candidate master TFs for the Luminal bladder cancer subgroup." (PMID 36944729, 2023). "Additionally, of the 24 TCGA cancer types, an inverse association between FOXA1 and CD274 gene expression was most significant in bladder cancer." (PMID 36323682, 2022). "Moreover, FOXA1 was indicated to be the independent predictor of poor prognosis of bladder cancer and also a marker of luminal and basal subtypes in bladder cancer." (PMID 33323547, 2020).
bladder cancer (continued). "Based on our in vitro and in vivo results, we conclude that silencing LINC00482 could down-regulate the expression of MMP15 via targeting FOXA1, which results in the inhibition of proliferation, migration, invasion of bladder cancer." (PMID 33323547, 2020). "In the current study, our findings suggested that silencing LINC00482 could potentially inhibit the proliferation, migration, invasion of bladder cancer cells through the up-regulation of MMP15 via recruiting FOXA1." (PMID 33323547, 2020). "Moreover, we found that silencing LINC00482 inhibited inflammation and angiogenesis in bladder cancer through the down-regulation of MMP-15 by targeting FOXA1, along with decreased levels of TNF-α, IL-1β, and IL-6 as well as the expression of VEGF and NF-κB." (PMID 33323547, 2020). "In our studies, treatment with TG did result in the differentiation of the As3+-transformed cells based upon morphological changes and induced the expression of PPARγ as well as FOXA1 both of which are factors known to drive luminal differentiation of bladder cancer cell lines." (PMID 32822399, 2020). "Conditional inactivation of both Pten and Foxa1 in intermediate/luminal cells in mice resulted in development of bladder cancer exhibiting squamous features, which suggested that hypermethylation of FOXA1 and allelic loss of PTEN drives squamous differentiation and promotes heterogeneity." (PMID 32842545, 2020). "The underlying mechanism how LINC00482, FOXA1 and MMP15 function in bladder cancer was further investigated to study the underlying mechanisms, bladder cancer cells were transfected with sh-MMP15, sh-NC, oe-LINC00482 + oe-FOXA1 + sh-MMP15, or oe-LINC00482 + oe-FOXA1 + sh-NC." (PMID 33323547, 2020). "Breast and bladder cancer express the second and third highest levels of FOXA1, respectively." (PMID 30272002, 2018). "Therefore, while we must be cautious in how we interpret this data, our approach validates the importance of PPARɣ and additionally shows a direct impact of GATA3 and FOXA1 on the expression of markers of the luminal molecular subtype of bladder cancer." (PMID 27924948, 2016). "Taken together, these results indicate that loss of FOXA1 expression is associated with decreased or absent UPK expression in widely used human bladder cancer cell lines and in a subset of human bladder tumor tissue." (PMID 22590586, 2012). "Although decreased FOXA1 expression appeared to be correlated with diminished UPK expression in commonly used bladder cancer cell lines, and in a minority of human cystectomy samples, the AUM antibody used for these studies recognizes all members of the uroplakin family." (PMID 22590586, 2012). "In the context of bladder cancer, the FOXA1 expression can be altered according to different molecular subtypes, with elevating in luminal molecular subtype whereas diminishing in basal molecular subtype, which is in keeping with the pattern of FOXA1 expression during urothelial differentiation." (PMID 38425344, 2024). "This is especially prevalent in bladder cancer, where our reanalysis of published data indeed indicated the repression of NR3C1 expression by FOXA1." (PMID 38015476, 2024). "Malignant arsenite-transformed UROtsa cells mimic basal muscle-invasive bladder cancer and are characterized by low expression of luminal markers (GATA3, FOXA1)." (PMID 38539513, 2024). "In five bladder cancer datasets (TCGA-MIBC, GSE13507, GSE48075, GSE32894, and GSE48276), ERBB2 was highly positively correlated with GATA3 and FOXA1 but negatively correlated with CD44 and KRT5, suggesting that ERBB2 is a luminal marker to some extent." (PMID 39840049, 2024). "To better assess the role of FOXA1 in the regulation of bladder cancer SEs, we mapped FOXA1, CTCF (Insulator/enhancers) and H3K4me3 (Promoter) binding by ChIP-seq in two bladder cancer cell lines: SD48 (LumP) and 5637 (Ba/Sq)." (PMID 36944729, 2023).
bladder cancer (continued). "Previous work showed that the three master Luminal TFs (FOXA1, GATA3, and PPARG) had to be perturbed simultaneously to induce a cell identity switch from luminal to basal in bladder cancer cell lines." (PMID 36944729, 2023). "In conclusion, both FOXA1 and ZBED2 inhibit inflammatory response and promote bladder cancer cell survival." (PMID 36944729, 2023). "Our findings and functional assays on FOXA1 and ZBED2 demonstrate that the enhancer set and TF networks identified herein represent prime targets for further pre-clinical investigation for bladder cancer treatment." (PMID 36944729, 2023). "FOXA1 has been documented to bind to the promoter of KDM6A and PLOD2, thus promoting their transcription in bladder cancer and non-small-cell lung cancer, respectively." (PMID 35498155, 2022). "Bladder cancer of the luminal subtype expresses a set of markers found in urothelial I-cells and S-cells, including GATA3, FOXA1, and PPARG23,31,32." (PMID 34697317, 2021). "We determine the genome-wide transcriptome, enhancer landscape, and transcription factor binding profiles of FOXA1 and GATA3 in luminal and basal subtypes of bladder cancer." (PMID 33858483, 2021). "Our findings are largely in agreement with previously known work on the role of FOXA1 and GATA3 in the regulation and maintenance of oncogenic programs in luminal bladder cancers." (PMID 33858483, 2021). "The transcription factors PPARγ, FOXA1, and GATA3 play a role in the establishment of the luminal subtype of bladder cancer." (PMID 32822399, 2020). "We evaluated the clinical efficacy and prognosis of muscle-invasive bladder cancer according to the basal/squamous-like (BASQ) classification system based on immunohistochemical staining [CK5/6(+), CK14(+), GATA3(−), and FOXA1(−)]." (PMID 31500577, 2019). "In summary, our analysis identified a set of human cell lines suitable for the study of molecular subtypes in bladder cancer, and furthermore indicates a cooperative regulatory network consisting of GATA3, FOXA1, and PPARɣ drive luminal cell fate." (PMID 27924948, 2016). "To determine the extent of FOXA1 and FOXA2 expression in various stages of bladder cancer, we performed immunohistochemical analysis on human tumor samples." (PMID 22590586, 2012). "The fact that FOXA1 knockdown had little influence on RT4 invasiveness, while FOXA1 overexpression slowed T24 cell invasion in vitro may suggest that loss of FOXA1 expression may cooperate with inactivation of p 53 and or PTEN to promote aggressive behavior of bladder cancer cells." (PMID 22590586, 2012). "To investigate this more closely, we examined the relationship between FOXA1 and GR in bladder cancer, since it showed the highest negative correlation between the cancers." (PMID 38015476, 2024). "Finally, our work also uncovers a role for both FOXA1 and ZBED2 in the regulation of inflammation in bladder cancer." (PMID 36944729, 2023). "In bladder cancers, where GATA3 and FOXA1 may have characteristic altered gene expression, Hi-C has been used elegantly to detect patterns of CNV and SV." (PMID 35902807, 2022). "FOXA1 expression was adequate for separating non-basal subtype of bladder cancer from the basal subtype." (PMID 35068946, 2021). "While FOXA1 and GATA3 are known to have low expression in basal bladder cancer cell lines and tumors, the enrichment of forkhead and GATA motifs in open chromatins across BLCA cell lines suggests compensation by Forkhead and GATA factors other than FOXA1 and GATA3." (PMID 33858483, 2021). "The LncMAP analysis determined that LINC00482 formed lncRNA-TF-gene triplet in bladder cancer, among which FOXA1 formed 12 triplets, only secondary to SMARCC2 which formed 19 triplets but it has never been indicated to be associated with bladder cancer." (PMID 33323547, 2020).
bladder cancer (continued). "For example, in bladder cancer (BLCA) we have provided a list of 65, 208, and 65 genes that may be regulated by POU3F1, FOXA1, or CEBPA, respectively, by binding to a specific hypomethylated enhancer." (PMID 25994056, 2015). "While FOXA1 is expressed in normal adult murine and human urothelium, the extent of FOXA family member expression in bladder carcinoma is unknown." (PMID 22590586, 2012). "Additionally, muscle-invasive and high-grade bladder cancers are characterized by a considerable reduction in FOXA1 expression compared to non-muscle-invasive bladder cancer." (PMID 38539513, 2024). "Five of the 26 SMGs had not been reported as SMGs in bladder cancer in previous studies: CDKN1B (1.2%), ITK (1.8%), PRDM2 (3.1%), FOXA1 (2.7%), and BAP1 (1.8%)." (PMID 36495164, 2023). "Therefore, we used gene expression data following the individual and combined overexpression of GATA3 and FOXA1 in the presence and absence of PPARɣ agonist to identify additional transcriptional regulators that may play a role in the activation of a luminal bladder cancer-specific gene expression." (PMID 27924948, 2016). "By western blot analysis of FOXA1 in a subset of bladder cancer cell lines included in the CCLE data and cultured in our laboratory, we found that other than a small amount of FOXA1 detected in the “non-type” T24 cells, FOXA1 expression was restricted to the luminal bladder cancer cell lines." (PMID 27924948, 2016).